BRCA1 (BRCA1 DNA repair associated)
Diseases named in the same sentence as BRCA1 in open-access papers (continued):
Sharing a sentence is not in itself a finding about the gene and the disease.
breast tumors (continued). "Basal-like breast tumors were seen in 42.0% of patients who had low BECN1 but high BRCA1 expression but in only 0.7% of patients who had high BECN1 but low BRCA1 expression (P = 9.05E− 17 for the difference between groups)." (PMID 25825707, 2015). "We also analyzed a large cohort of breast tumor samples for BRCA1-IRIS, Forkhead box class O3a (FOXO3a) and survivin expression." (PMID 25583261, 2015). "Various degrees of BRCA-1 promoter CpG methylation have been observed in sporadic breast tumors ranging from ~10 to 85 % depending on tumor type (ductal invasive > lobulo-alveolar)." (PMID 26715507, 2015). "Our data highlighted the involvement of miR-573 and miR-578 in the VEGF, Focal Adhesion Kinase (FAK) and HIF-1 signaling pathways, highlighting their role in BRCA1/2-related breast tumor angiogenesis." (PMID 25333258, 2015). "BRCA1 splicing events were scanned in 70 breast tumor samples, 4 breast samples from healthy individuals and in 72 blood-derived samples by capillary electrophoresis (capillary EP)." (PMID 25884417, 2015). "For example, elevated genetic instability, such as in BRCA1 null and basal-like breast tumors cannot explain the marked epigenetic instability that we found in all subtypes." (PMID 25653311, 2015). "With this aim, we have characterized BRCA1 AS in 70 breast tumor samples and 4 healthy breast tissue samples." (PMID 25884417, 2015). "We previously showed that mammary adipocyte-specific PPARγ blocks breast tumour progression in part via upregulation of BRCA1." (PMID 25889730, 2015). "Previously, we showed elevated BRCA1-IRIS expression in approximately 80% of breast tumors (>800 tumor samples were analyzed) that was correlated with elevated p-AKT and survivin expression (Ref." (PMID 25583261, 2015). "Here we provide the first in vivo evidence that PPARγ activation in MG cells blocks breast tumour progression in PPARγ-WTs by upregulating BRCA1, and downregulating VEGF and Cox-2, expression." (PMID 25889730, 2015). "In humans, BRCA1-positive breast tumours are characterized by a large number of chromosomal changes, some of which differ depending on the genotype." (PMID 26061043, 2015). "We found that BRCA1 deficiency correlates with the repression of FOXA1 expression in mammary epithelial cancer cell lines and that BRCA1 mutation is significantly associated with FOXA1 promoter methylation and silencing in human breast tumours." (PMID 25531315, 2015). "Pit-1, BRCA1 and 18S mRNA expression were evaluated by real-time PCR on a cDNA microarray to explore the relationship between Pit-1 and BRCA1 in human breast tumors (n = 41)." (PMID 25992773, 2015). "BRCA1 and BRCA2 are the best-known cancer susceptibility genes associated with the hereditary breast tumors." (PMID 25333258, 2015). "Basal-like breast tumors were seen in 31.0% of patients who had low BECN1 but high BRCA1 expression but in only 4.3% of patients who had high BECN1 but low BRCA1 expression (P = 3.39E − 24 for the difference between groups)." (PMID 25825707, 2015). "Two potential strategies to compensate for the reduced BRCA1 expression in breast tumors are exploiting synthetic lethal interactions between reduced BRCA1 and other cellular pathways or inducing BRCA1 expression." (PMID 25762631, 2015).
breast tumors (continued). "Gene expression data: We have performed one of the largest gene expression profiling analyses of familial breast tumours (n = 74) and stratified them based on BRCA mutation status as BRCA1-, BRCA2- and non- BRCA1/2 tumours." (PMID 25521701, 2014). "Initial studies of LOH in the breast tumours of BRCA1 carriers reported a rate of 75% (75/101) of LOH of the wild type allele." (PMID 24950059, 2014). "• apply the model on two case studies - normal vs PDAC tumour and BRCA1 vs BRCA2 familial breast tumour conditions - to decipher their roles in these tumours." (PMID 25521701, 2014). "It is well established that BRCA1-related breast tumors, as a group, differ from non-BRCA1 tumors in terms of histological phenotype." (PMID 25857409, 2014). "We provide evidence that, rather than being a passenger alteration derived from the increased genomic instability shown by basal-like and BRCA1 primary breast tumors, CUL4A overexpression would confer selective advantage to tumor cells." (PMID 24870930, 2014). "In the present study, frozen primary breast tumor samples were collected from 70 non-BRCA1/2, 33 BRCA1, 22 BRCA2, and 128 sporadic cases." (PMID 24479546, 2014). "Familial non-BRCA1/2 breast tumors comprising a molecularly heterogeneous group of cancers can be further classified by RNA profiling into subgroups showing high resemblance to the intrinsic molecular subtypes." (PMID 24479546, 2014). "In our study, BRCA1 promoter methylation was detected in breast tumors from both women in a family with basal-like tumors (Family 031)." (PMID 24479546, 2014). "In the current study, we have characterized breast tumors from female carriers of germline mutations in BRCA1 and BRCA2 genes and a cohort of sporadic (unselected) breast tumors by microarray gene-expression analysis." (PMID 23704984, 2013). "It is hoped that this novel treatment will benefit both familial and sporadic ovarian or breast tumours that lack BRCA1/2 expression." (PMID 23536787, 2013). "The incidence of BRCA1 methylation has previously been reported to be higher in breast tumors of infiltrating ductal type." (PMID 23405268, 2013). "In contrast, the vast majority of tumors arising in BRCA2 carriers were ER+, and only very few of the BRCA1/2 positive breast tumors demonstrated HER2-amplification." (PMID 23704984, 2013). "In FFPE tissue, with MS110 antibody staining, we frequently found reduced BRCA1 nuclear staining in breast tumor tissue compared to normal tissue, and less BRCA1 staining with higher histological grade in the tumors." (PMID 23855721, 2013). "BRCA1 mutant breast tumours have been reported to express higher levels of JAG1 mRNA compared with BRCA2 mutant tumours; however, this was not significant." (PMID 23863842, 2013). "The association between BRCA1-IRIS overexpression and overexpression/activation of AKT and survivin in breast tumors." (PMID 22511931, 2012). "First, we immunohistochemically stained and analyzed a large cohort of primary breast tumor samples using a newly generated BRCA1-IRIS monoclonal antibody." (PMID 22511931, 2012). "We found that BRCA1-IRIS is overexpressed in the majority of breast tumors analyzed, especially those of the HER2+ and TN/BL subtypes." (PMID 22511931, 2012).
breast tumors (continued). "BRCA1-IRIS overexpression triggers aggressive breast tumor formation, especially in patients with HER2+ or TN/BL subtypes." (PMID 22511931, 2012). "Familial BRCA1 breast tumours are characterised by basal-like phenotype and high-histological grade which are typically associated with increased genomic instability." (PMID 22434526, 2012). "Taken together, these data show that BRCA1-IRIS is overexpressed in two of the most aggressive breast tumor subtypes and that its overexpression correlates with increased AKT and survivin in these tumors." (PMID 22511931, 2012). "Here, we show that BRCA1-IRIS overexpression in breast tumor cells is, at least partially, BRCA1/p220-dependent." (PMID 22431556, 2012). "LOH at 17q has been detected in about 30%–60% of sporadic breast tumors and, in many instances, includes the BRCA1 locus." (PMID 22347400, 2012). "Wild-type BRCA1 is required for the inhibition of the growth of breast tumor cells in response to the pure steroidal ERα antagonist fulvestrant." (PMID 23203101, 2012). "Wild-type BRCA1 is required for the inhibition of growth of breast tumor cells in response to the pure steroidal ERα antagonist fulvestrant." (PMID 23203101, 2012). "Earlier publications have also shown a range of expression and subcellular localization of BRCA1 from nuclear to cytoplasmic in breast tumour cells and nuclear staining in normal tissues." (PMID 23508738, 2011). "In contrast, the immunohistochemical expression of BRCA1 within the breast tumours was broadly heterogeneous and the intensity of staining was lower than in the normal breast." (PMID 23508738, 2011). "The resulting training set consisted of 84 breast tumours: 39 BRCA1-likeaCGH and 45 Sporadic-likeaCGH tumours." (PMID 22032731, 2011). "To evaluate the relationship between BRCA1 expression and the breast CSC marker CD44, we correlated the cytoplasmic and nuclear expressions of BRCA1 with the level of expression of CD44 obtained from our previous study in the same series of breast tumours." (PMID 23508738, 2011). "The pattern of BRCA1 expression was then correlated with expression of CD44 (CD44+ cancer stem cell phenotype) in the same collection of breast tumours." (PMID 23508738, 2011). "Here we have identified for the first time the arginine and lysine methylation of BRCA1 in tissue culture cell lines as well as breast tumor tissue samples." (PMID 20614009, 2010). "Further research will be needed to examine the potential of the data presented here to predict BRCA1 or BRCA2 abnormalities in an independent population of breast tumours or cell lines." (PMID 19589159, 2009). "This suggests that inactivation of the BRCA1 gene through epigenetic silencing is an important event in sporadic breast tumour development." (PMID 19589159, 2009). "Here, we used expression profiling to classify the BRCA1 breast tumours and applied an integrative approach to examine biological dependencies and differences." (PMID 19826428, 2009). "We suggest that BRCA1 breast tumours show a high degree of molecular complexity and define the wiring diagram of signalling pathways involved in their tumorigenesis." (PMID 19826428, 2009). "The results are in agreement with other series in which the percentage of BRCA1 breast tumours showing a basal phenotype defined by immunohistochemical markers ranges from 44% to almost 100%." (PMID 19826428, 2009). "All together these experimental observations suggest that sensitivity to platinum derivatives inversely correlates to sensitivity to paclitaxel in BRCA1-defective breast tumor cells." (PMID 19825178, 2009).
breast tumors (continued). "The involvement of the BRCA1 and BRCA2 genes in sporadic breast tumour development has been questioned because somatic mutations in BRCA1 or BRCA2 have not been found." (PMID 19589159, 2009). "To validate the relationship with BRCA1 abnormalities we obtained previously published CGH array data in which five familial BRCA1 breast tumour samples were analysed." (PMID 19589159, 2009). "This study reveals the molecular complexity of BRCA1 breast tumours, which are found to display similarities to sporadic tumours, and suggests possible prognostic implications." (PMID 19826428, 2009). "Only resveratrol (3,5,4'-trihydroxy-trans-stilbene), a dietary constituent found in grapes and wine, has been found to exert anticancer activity by targeting BRCA1 in breast tumor cell lines." (PMID 18348714, 2008). "Our previous study using an ovarian granulosa cell line KGN showed that the breast tumor suppressor BRCA1 is involved in down-regulating aromatase expression." (PMID 19568323, 2008). "Our investigations into the interaction of BRCA1 with PP1 led us to examine the expression levels of BRCA1, PP1α, β and γ in primary human breast tumors." (PMID 17511879, 2007). "Decreased transcription of the BRCA1 gene has previously been observed to occur in sporadic breast tumours, making elucidation of the mechanisms regulating the expression of this gene important for our understanding of the etiology of the disease." (PMID 17663789, 2007). "As was expected, other genes showing relatively high percentages of LOH in breast tumors were BRCA1 (52%) and MRE11A (50%)." (PMID 17280605, 2007). "Following mRNA expression analysis, we identified low levels of BRCA1 and variable levels of PP1α and β in primary sporadic human breast tumors." (PMID 17511879, 2007). "We examined the frequency of BRCA1 methylation in 143 primary sporadic breast tumours along with BRCA1 copy number alterations and tumour phenotype." (PMID 16846527, 2006). "Our results show promoter hypermethylation of the BRCA1 gene in a considerable proportion of all primary sporadic breast tumours." (PMID 16846527, 2006). "Familial BRCA1 and BRCA2 tumours are associated with young age of onset and are phenotypically distinct from each other as well as from sporadic breast tumours." (PMID 16846527, 2006). "This motif, originally identified in the human breast tumor suppressor gene BRCA1, is a protein interaction domain." (PMID 17094803, 2006). "Histopathological features of BRCA1 and BRCA2 tumours have previously been characterised and compared with unselected breast tumours; however, familial non-BRCA1/2 tumours are less well known." (PMID 15642173, 2005). "Loss of Fhit expression was significantly more frequent in the BRCA1 cancers compared with sporadic breast tumours (9% Fhit positive vs 68% Fhit positive), suggesting that the BRCA1 pathway is also important in protecting the FRA3B/FHIT locus from damage." (PMID 12771912, 2003). "In addition, bioinformatics analysis results had confirmed that SOSTDC1 expression was higher in BRCA1‐mutant breast tumor patients." (PMID 38864559, 2024). "Hu and colleagues performed scRNA-seq on breast tumors from BRCA1 mutation carriers and noncarriers and found similarities between basal-like tumors and the expanded, abnormal luminal progenitor population seen in BRCA1 carriers, and between ER-positive (ER+) breast tumors and luminal mature cells." (PMID 39478117, 2024). "Moreover, PARP10 depletion in BRCA1-mutant breast tumor-derived MDA-MB-436 cells also increased gap formation upon exposure to 0.4 mM HU or 150 μM cisplatin." (PMID 39043663, 2024). "Notably, the inactivation of BRCA1 through epigenetic mechanisms in sporadic breast tumors elicits similar effects to those observed in genetically inherited cases with BRCA1 mutations." (PMID 39338894, 2024). "Their study included 30 familial non-BRCA1/BRCA2 breast tumours." (PMID 37316882, 2023).
breast tumors (continued). "Database analysis shows that NORE1A loss of expression is common in primary breast tumors and correlates with BRCA1 loss in Her2+ but not Her2− cases." (PMID 37627161, 2023). "Other classifiers based on variable numbers of miRNAs have been suggested to distinguish BRCA1/2-mut (n = 6) and hereditary breast cancers (n = 15) from non-mutated breast tumours, respectively, with relatively high accuracy." (PMID 36831687, 2023). "Our results, supported by the literature, propose BRCA1 promoter hypermethylation as a potential useful biomarker for breast tumor aggressiveness, as well as an early biomarker for both BBLs at risk to progressing into cancer and NATs harboring the tumors at risk of recurrence." (PMID 37761820, 2023). "In Brca1-knockout mice, breast tumor onset could statistically significantly be delayed after oophorectomy: median tumor onset was 300 days post-oophorectomy vs. 206 days without oophorectomy (HR 0.46, 95% CI 0.18–1.18, p 0.049)." (PMID 37046756, 2023). "Thus, the aim of the work was to evaluate the predictive and prognostic potential of DNA copy number aberrations and mutations in the BRCA1, BRCA2, and PALB2 genes in breast tumors." (PMID 37628606, 2023). "The BRCA1 tandem duplication of exon 13 carried by patient 20X0146 was detected thanks to a pseudo circular RNA of exon 13 that is found in normal salpingian and ovarian tissue and in breast tumor tissue." (PMID 37046838, 2023). "Furthermore, the corresponding patient was diagnosed with a BRCA1/2 deletion in the breast tumor sample and therefore had previously received treatment with the PARP inhibitor Olaparib." (PMID 37509265, 2023). "Finally, we observed a concordance (60%) in BRCA1 promoter hypermethylation status between malignant breast tumors and their paired histologically normal adjacent tissues." (PMID 37761820, 2023). "Interestingly, a positive correlation is found between TGF-β expression level and miR-181/BRCA1 pathway activation in primary breast tumor samples." (PMID 35392236, 2022). "In view of the fact that IGF1 is mainly produced by stromal cells whereas IGF2 biosynthesis occurs directly in breast tumor cells, data indicate that BRCA1 gene expression is potentially regulated by both autocrine (IGF2) and paracrine/endocrine (IGF1) stimuli." (PMID 35432218, 2022). "Bi-allelic loss of BRCA mutations was seen to be frequent in both germline and somatic mutations, ranging from 81 to 100% for BRCA1 and 92 to 100% for BRCA2 mutations (germline and somatic) for ovarian tumours and 83–96% and 78–80%, respectively in breast tumours." (PMID 34979999, 2022). "Based on the enhanced MRI of breast tumors and the subregions generated according to the habitat imaging theory, the parameters extracted to describe the clustering effect could reflect the BRCA1 status." (PMID 35402620, 2022). "Therefore, ablation of BRCA1 via lessened SIRT1 resulted in an upregulation of Survivin that facilitated the growth of breast tumors." (PMID 36185256, 2022). "Indeed, downregulation of BRCA1 protein induced by overexpression of miR-182 was sufficient to impair HR-mediated repair and hypersensitize breast tumor cells to PARPi." (PMID 35203410, 2022). "Breast tumors with BRCAness have deficiencies in homologous recombination repair (HRR), like BRCA1/2-mutation carriers, and consequently could benefit from poly-(ADP)-ribose polymerase (PARP) inhibitors and DNA-damaging chemotherapy." (PMID 35715772, 2022). "Our results are consistent with two prior studies that have reported lower levels of methylation in breast tumor tissue from BRCA1 mutation carriers compared to noncarriers." (PMID 39741654, 2022).